S100A9 (S100 calcium binding protein A9)
Diseases named in the same sentence as S100A9 in open-access papers (continued):
Sharing a sentence is not in itself a finding about the gene and the disease.
lung carcinoma (27 papers, 2012 to 2026). "It was noted that a greater expression of S100A9 was associated with a lower overall survival rate both in patients with ungrouped lung cancer and patients with lung adenocarcinoma." (PMID 37533789, 2023). "Blood monocytic S100A9+ MDSC counts were higher in lung cancer patients than healthy donors, and were associated with poor treatment response and shorter progression-free survival (PFS)." (PMID 29484139, 2018). "Through integrative transcriptomic, proteomic, and secretomic analyses in a murine model of lung cancer-induced cachexia, we identify S100A9 as a key factor selectively upregulated and secreted by brown adipocytes." (PMID 42069727, 2026). "In any case, besides the results in sarcoma and head and neck cancer, other authors reported associations of S100A9 inflammatory cells with good prognosis in gastric cancer, as well as therapeutic interventions with recombinant S100A8 in lung cancer." (PMID 39563958, 2024). "S100A8 and S100A9 were found increased in inflammatory diseases and cancers including osteosarcoma, lung carcinoma, and cervical cancer." (PMID 39575241, 2024). "The correlation between IL-10 and S100A9 gene expression in lung cancer was analyzed using the Gene Expression Profiling Interactive Analysis database, and it showed a positive correlation between IL-10 and S100A9 (R = 0.4, P < 0.001)." (PMID 37533789, 2023). "We previously showed that treatment with anti-S100A8/S100A9 antibodies inhibited metastasis in mouse lung carcinoma (3LL)-bearing mice." (PMID 36932197, 2023). "We observed S100A8+ and S100A9+ myeloid cells infiltrating growing lung cancers at midpoint of survival in the orthotopic LLC lung tumour mouse model; PMN-MDSC were the predominant myeloid subset, as reported by others." (PMID 35655772, 2022). "S100A9 levels in lung cancer brain metastases obtained by neurosurgery correlated with the time for brain relapse after WBRT, as measured by follow-up magnetic resonance imaging (MRI)." (PMID 35411077, 2022). "Some of these proteins, such as Annexin A2 and S100A9, are involved in regulation of immune escape in some cancer types, including lung cancer." (PMID 33546102, 2021). "Dermcidin has also recently been proposed as a prognostic biomarker of lung cancer together with S100-A9." (PMID 33396627, 2020). "In lung cancer and invasive ductal carcinoma of the breast, overexpression of S100A9 in cancer cells has been shown to contribute to the development and progression of cancer." (PMID 22838504, 2012). "Additionally, S100A9 is often elevated in various cancers including breast, prostate, colorectal, and lung cancers." (PMID 40565156, 2025). "We found that S100A9 was highly expressed in lung cancer patients compared to other cancer types." (PMID 41173834, 2025). "In addition, studies using a mouse lung cancer model have found that the S100A8/S100A9–EMMPRIN–Vegfa axis promotes tumor angiogenesis and progression, which is associated with the prognosis of lung cancer patients." (PMID 37701037, 2023). "In addition, we explored the potential relationship between the expression levels of S100A9 and human lung cancer progression." (PMID 37533789, 2023). "Studies using S100A9 knockout mice, or mice implanted with lung cancer cells in which S100A9 gene expression was silenced, reported that S100A9 promotes MDSC accumulation in the lungs and may contribute to increased metastasis to the liver." (PMID 35655772, 2022). "Mononuclear MDSCs can further mature into TAMs in tumor microenvironment in mice model, but the association of S100A9+ monocytic MDSCs and TAMs in lung cancer patient is not clear." (PMID 29484139, 2018). "The expression rates of S100A9 and S100A8 were significantly higher in lung cancer tissues than in para-cancer tissues, and their expression was associated with tumor differentiation degree." (PMID 39516272, 2025).
lung carcinoma (continued). "To explore the clinical significance of S100A9 in SCLC, we analyzed the protein expression of S100A9 in a lung cancer patient tissue microarray by immunohistochemistry (IHC)." (PMID 41173834, 2025). "In lung cancer, S100A8 and S100A9 are expressed in both cancer and stromal cells and high expression has been correlated with positive and negative clinical outcomes." (PMID 35655772, 2022). "MDMs from lung cancer patients (CA-MDM), being derived from S100A9-enriched monocytes, retained higher expression of S100A9 and expressed stronger CD206, a marker for M2 macrophages." (PMID 29484139, 2018). "We also found that protein S100-A9, extracellular superoxide dismutase [Cu-Zn], and matrix metalloproteinase 9 may represent potential serological markers for TB to distinguish patients with this disorder from healthy controls or those with pneumonia or lung cancer patients." (PMID 28278182, 2017). "HMGB1, S100A9, and HSP90 were shown to be predictive and prognostic markers for distinguishing cancer patients from healthy controls in several cancer types such as mesothelioma, colorectal, gastric, and lung cancers." (PMID 39768997, 2024). "Immunohistochemical analysis using specific anti-S100A8 and S100A9 antibodies detected S100A8+ and S100A9+ myeloid cells infiltrating lung cancers (8 cells per field of view), but not in lung tumor cells." (PMID 35655772, 2022).
systemic lupus erythematosus (26 papers, 2013 to 2025). An autoimmune multi-organ disease typically associated with vasculopathy and autoantibody production. "Recent research suggests that S100A9 is a crucial pro-inflammatory pathogenic molecule that is extensively expressed in several autoimmune diseases, including systemic lupus erythematosus, rheumatoid arthritis, and Sjögren’s syndrome." (PMID 40346703, 2025). "We further analyzed the effect of S100A9 deficiency on macrophage activation in IMQ-induced lupus mice." (PMID 38429401, 2024). "Further understanding the mechanism behind lupus-like disease development in S100a9-deficient male NZBWF1 mice is imperative for the identification of de novo molecular or cellular therapeutic targets." (PMID 34220829, 2021). "A previous study showed that S100a9 protected male lupus-prone NZBWF1 mice from disease development." (PMID 39175079, 2024). "Further studies are needed to identify the subcellular localization and post-translational modification status of S100a9 (and S100a8) in male and female lupus-prone NZBWF1 mice and SLE patients." (PMID 34220829, 2021). "We isolated Gr1highCD11b+ and Gr1lowCD11b+ cells from 9 week old male and female NZBWF1 lupus-prone mice and determined levels of S100a4, S100a8, and S100a9 mRNA." (PMID 34220829, 2021). "Efficacy of S100A9 blocking by paquinimod was already shown in several mouse models of inflammatory diseases including experimental autoimmune encephalitis 54, liver fibrosis 55, lupus-prone MRL-lpr/lpr mouse model 56, and skin fibrosis." (PMID 35198063, 2022). "Interestingly, TNF, IL-17, IL-1, and S100A8/S100A9 have been described to form a positive feedback network driving disease activity in murine models of auto-immune arthritis or systemic lupus erythematosus." (PMID 33643287, 2020). "Clinical data suggest that, compared with those in patients with inactive SLE and healthy individuals, the expression of S100A8 and S100A9 in patients with active SLE is significantly elevated and positively correlated with systemic lupus erythematosus disease activity index (SLEDAI) scores." (PMID 38429401, 2024). "In summary, S100a9 is expressed and secreted by myeloid cells, including MDSCs, and exerts an immunosuppressive role in male, but not female, lupus-prone NZBWF1 mice." (PMID 34220829, 2021). "In contrast, immunization of S100a9+/+, S100a9+/- and S100a9-/- female NZBWF1 mice resulted in similar levels of NP-specific antibodies between the strains, suggesting a sex-specific effect of S100a9 in NZBWF1 lupus-prone mice." (PMID 34220829, 2021). "Based on studies suggesting a role for S100a9 in MDSC-driven immunosuppression in cancer, we hypothesized that MDSCs utilized S100a9 to inhibit immune activation and disease progression in NZBWF1 lupus-prone males." (PMID 34220829, 2021). "Similar results were also obtained in the lymph nodes, where S100A9 deletion significantly reversed the activation of macrophages and DCs, reduced the activation of B cells and CD4+ T cells and decreased the percentage of germinal center B cells and plasmacytes in the mLNs of IMQ-induced lupus mice." (PMID 38429401, 2024). "Similar results were also obtained coincidentally in the lymph nodes, where mice that received S100A9−/−-MDSCs showed markedly reduced activation of B cells and CD4+ T cells as well as decreased percentage of germinal center B cells and plasmacytes in the mLNs of IMQ-induced lupus mice." (PMID 38429401, 2024). "TLR activation by S100A9, alongside TLR–TNFSF13B interaction, cooperatively enhanced survival signals delivered to myeloma cells, consistent with the previous finding that TLR+ plasma cells showed higher level of autoantibodies against dsDNA in TNFSF13B-dependent lupus." (PMID 34150664, 2021).
periodontitis (23 papers, 2011 to 2025). An acute or chronic inflammatory process that affects the tissues that surround and support the teeth. "Mendelian randomization studies demonstrated that elevated circulating neutrophil levels causally increase periodontitis risk, while S100A9 emerges as a protective factor against disease progression and therapeutic targets." (PMID 41009952, 2025). "In this study, we also analysed the abundance of proteins, such ashaptoglobin, S100A9 and Albumin, all previously linked to periodontitis." (PMID 40230956, 2024). "In the late stages, S100a8 and S100a9, which encode damage-associated molecular patterns, and Cxcl5 and Cxcl3, which encode chemokines, are prominently upregulated, highlighting the persistent recruitment of neutrophils, a hallmark of periodontitis." (PMID 40076622, 2025). "Periodontitis induced the development of GMPs toward the neutrophil lineage at the expense of monocytic differentiation, as indicated by the dynamic changes in monocytic signature genes (F13a1, Irf8, and Ly86) and neutrophil-associated genes (Camk1d, S100a8, and S100a9) along the trajectory." (PMID 40521205, 2025). "Furthermore, inhibition of histones, a major component of NETs, substantially reduces upregulation of IL‐17‐related genes (IL‐17a, S100a9, and IL‐6), decreases IL‐17‐positive cells and Th17 cells accumulation, and subsequently protects against periodontal bone loss in periodontitis." (PMID 41031144, 2025). "Similarly, GCF fluid containing S100A8 and S100A9 was associated with periodontitis." (PMID 34372836, 2021). "A cross-sectional study reported gingival crevicular fluid S100A9 levels were lower in established periodontitis patients compared to healthy controls, and S100A9 levels showed screening ability for periodontitis." (PMID 41009952, 2025). "Among 18 evaluated genes, most genes were significantly upregulated in periodontitis tissue compared to controls, while S100A9 was downregulated." (PMID 41009952, 2025). "On the other hand, increased level of proteins S100-A8 and S100-A9 is treated as a marker of periodontitis, indicating that an imbalance of these 2 proteins can cause oral pathological states." (PMID 36949424, 2023). "In recent years, saliva S100A8 and S100A9 have been shown to be promising biomarkers for periodontitis." (PMID 35315933, 2022). "According to our knowledge, there are no other previous studies on the association between genetic polymorphisms of S100A8, S100A9, or S100A12 and periodontitis." (PMID 35315933, 2022). "Recently, a Korean study reported that salivary S100A9 was also decreased in periodontitis patients compared to healthy participant." (PMID 34372836, 2021). "This study aimed to compare the association and screening ability of S100A8 and S100A9 in saliva, blood and gingival crevicular fluid (GCF) for periodontitis status." (PMID 34372836, 2021). "In the present study, we focused on the effects of S100A8 and S100A9 on expressions of proinflammatory- and bone metabolism-related factors in osteocytes to elucidate mechanisms in aggravation of periodontitis." (PMID 32149126, 2020). "Taken together, S100A8 and S100A9, in periodontal tissue, have essential roles for the progression of periodontitis." (PMID 31605018, 2019). "In accordance with a previous report, myeloperoxidase, myosin 9, annexin A3, profilin-1, L-plastin (plastin-2/LCP1), S100A8, and S100A9 were detected at higher levels in chronic periodontitis patients compared to healthy individuals." (PMID 21794177, 2011). "Additionally, increased infiltration of S100A9-labeled leukocytes was observed in the periodontitis mice." (PMID 40303304, 2025). "In a study of experimental periodontitis in mice that compared wild type and S100A9−/− (calprotectinnull), expression of calprotectin minimized the emergence of a dysbiotic periodontal microflora, gingival inflammation, and periodontitis with loss of alveolar bone." (PMID 35979535, 2022).
periodontitis (continued). "Thus salivary S100A8 and S100A9 have been specific targets for researcher and practitioners who are interested to identify periodontitis using robust and cost-effective method." (PMID 34372836, 2021). "Hence, the present study aimed to compare the association and screening ability of S100A8 and S100A9 in saliva, blood and GCF according to the periodontitis status." (PMID 34372836, 2021). "Moreover, the ratio S100A8/S100A9 and the metalloproteinase-8 in saliva could differentiate distinct periodontitis groups." (PMID 37224160, 2023). "Moreover, the ratio S100A8/S100A9 in saliva can differentiate distinct groups of periodontitis." (PMID 37224160, 2023). "Thus, the hypothesis of this study was that S100A8 and S100A9 in saliva, blood and GCF show the difference in the association and screening ability of S100A8 and S100A9 in saliva, blood and GCF according to the periodontitis status." (PMID 34372836, 2021). "Therefore, the protective role of anti-S100A9 might facilitate the treatment of periodontitis; ongoing in vivo trials using anti-S100A9 might support this." (PMID 25338166, 2014). "Toll-like receptor 4 (TLR4) is described as the receptor of S100A9, so we further explored the transformation of TLR4 signaling way in the model of high-sugar-induced periodontitis." (PMID 40173189, 2025). "According to the bioinformatic analysis and experiment results, S100A9 was finally determined as the hub gene, which was up-regulated in DM2 and periodontitis." (PMID 40173189, 2025). "A number of these genes were also significantly increased in aging and periodontitis tissues (e.g., ANXA1, HMGB1, S100A8, S100A9, APOE/ß2-GPI, LTF, TSLP)." (PMID 38098978, 2023). "S100A8, S100A9, S100A12, were all elevated in saliva from periodontitis and gingivitis patients compared to healthy controls and salivary levels of S100A8, S100A9 and S100A12 were significantly related to clinical and radiographic signs of periodontitis." (PMID 38098978, 2023). "Contrary to previous studies, salivary S100A9 in our data was negatively correlated to that of GCF, especially in periodontitis patients." (PMID 34372836, 2021). "T-test, analysis of covariance, Mann–Whitney test and correlation analysis were applied to compare the relationship of S100A8 and S100A9 in saliva, blood, and GCF for periodontitis." (PMID 34372836, 2021). "Our data showed that salivary S100A8 had the most appropriate screening ability for periodontitis among S100A8 and S100A9 in saliva, blood and GCF." (PMID 34372836, 2021). "In a recent study, high levels of calprotectin were detected in gingival crevicular fluid (GCF) from patients with periodontitis, and high levels of S100A8 and S100A9 were also detected in blood vessels in Pg-infected mice." (PMID 32149126, 2020). "Notably, four of these high-confidence genes were found to be involved with multiple phenotypes: S100A9, S100A12 (neutrophils and periodontitis); MCM6, P14KAP2 (neutrophils and pDC)." (PMID 38536078, 2024). "The high-confidence genes S100A9 and S100A12, located on 1q21.3, could potentially serve as immunomodulatory targets for neutrophil-mediated periodontitis." (PMID 38536078, 2024). "(D) Regional Manhattan plot of conditional analysis for S100A9, S100A12 in periodontitis." (PMID 38536078, 2024). "Among the studied polymorphisms of CFH, MMP8, and S100A8/S100A9/S100A12 gene region, those located in the CFH gene associated with periodontitis, whereas the ones near S100A9 or in the MMP8 gene did not." (PMID 35315933, 2022). "In blood, the adjusted value of S100A8 and S100A9 were not significantly different according to periodontitis status (ANCOVA, p > 0.05)." (PMID 34372836, 2021). "However, the adjusted values of S100A8 and S100A9 in GCF were higher by around 2.5 times in NIPERIO participants than in stage II and stage III–IV periodontitis participants (ANCOVA, p < 0.05)." (PMID 34372836, 2021).
periodontitis (continued). "As to established periodontitis, salivary S100A8 could be the best consistent biological marker among S100A8 and S100A9 in saliva, GCF and blood." (PMID 34372836, 2021). "Polymorphisms of S100A9 or MMP8 did not associate with any periodontal parameters, whereas polymorphisms in CFH gene as well as saliva TCC concentrations were associated with clinical and radiographic signs of periodontitis." (PMID 35315933, 2022). "Finally, we suggest that S100A9-RAGE and -TLR4 pathways in osteocytes may be potential targets for the therapy against bone destruction mediated by the host immune and inflammatory responses to the microbial challenge, such as periodontitis." (PMID 32149126, 2020).